MIR6511A4 (microRNA 6511a-4)
Synonyms: hsa-mir-6511a-4; MIR6511A-4
Gene: MicroRNA gene on chromosome 16 (18,344,013 to 18,344,079, reverse strand). Ensembl gene ENSG00000273613.
Homologues: Paralogues in human: MIR6511A1 (100% identical), MIR6511A2 (100% identical), MIR6511A3 (100% identical).